SDHB (succinate dehydrogenase complex iron sulfur subunit B)
Diseases named in the same sentence as SDHB in open-access papers (continued):
Sharing a sentence is not in itself a finding about the gene and the disease.
pheochromocytoma (continued). "The successful distinction of tumors from Cluster 1 and Cluster 2 by SDHB immunostaining in our pilot series suggests that this may be developed into a new screening method to classify pheochromocytomas in one of two major categories that reflect the underlying genetic defect." (PMID 16103922, 2005). "Further work is required to define the precise mechanism of SDHB tumour suppression and how these explain the restricted phenotype of SDHB-associated tumours and the lack of evidence for a role of somatic SDHB inactivation in the pathogenesis of sporadic phaeochromocytomas." (PMID 15505628, 2004). "However, to investigate further the potential role of SDHB in the pathogenesis of phaeochromocytoma, we determined the frequency, extent and patterns of 1p allele loss in 36 sporadic phaeochromocytomas using 14 polymorphic microsatellite markers mapping to 1p22–1p36." (PMID 15505628, 2004). "In preclinical models of SDHB-mutant pheochromocytomas/paragangliomas, olaparib has been shown to enhance the effect of temozolomide." (PMID 40649858, 2025). "Hereditary pheochromocytoma and paraganglioma (hPPGL) is caused by pathogenic mutations in succinate dehydrogenase (SDH) genes, commonly SDHB." (PMID 41252211, 2025). "Isolated deletion of SDHB caused an obesity phenotype that was similar to SDHC deletion, and codeletion of SDHB and NF1 resulted in development of SDHB‐deficient pheochromocytomas." (PMID 39399478, 2024). "Mutation in SDHD gene is predominant in head and neck PGLs and has a better prognosis than SDHB-related pheochromocytomas/PGLs." (PMID 39156002, 2024). "Only a limited number of PAs in association with SDHB-related PGL has been reported and the vast majority occurred subsequently or simultaneously with pheochromocytoma/PGL (collectively abbreviated as PPGL)." (PMID 38152133, 2023). "It has been reported that SDHB gene knockout in the human pheochromocytoma cell line (HPheo1) up-regulates genes involved in glycolysis and down-regulates genes involved in OXPHOS." (PMID 36949947, 2023). "Hypermethylation has been previously reported in other manifestations of germline SDHB mutation, including paraganglioma (PGL), pheochromocytoma (Pheo) and the gastro-intestinal stromal tumors (GIST) associated with SDH subunit gene mutation." (PMID 36455002, 2022). "Genomic analysis of familial PGL/pheochromocytoma (PCC) has shown that while mutations of SDHD and SDHC are associated with PGL1 and PGL3, mutations in the large subunit genes SDHB, SDHA and SDHAF2 are associated with PGL4, PGL5 and PGL2." (PMID 35382567, 2022). "We confirmed elevated SUCNR1 expression in SDHx PPGLs and after SDHB knockout in progenitor cells derived from a human pheochromocytoma (hPheo1)." (PMID 33776908, 2021). "Pathology was consistent with pheochromocytoma with tumour cells reactive with chromogranin, synaptophysin and S100; there was also presence of granular cytoplasmatic immunoreactivity for SDHB; proliferative index was low and PASS Score was 0/20." (PMID 33815275, 2021). "Metastatic pheochromocytomas and paragangliomas with reduced SDH expression due to SDHB mutations, show an EMT signature based on transcriptomics analysis and increased SNAIL 1/2 protein expression." (PMID 32318352, 2020). "We reasoned that these structural events are likely to be important in co-operating with SDHB loss of function to promote tumorigenesis, and provide further evidence that RS0 has the genomic hallmarks of human SDHB pheochromocytoma." (PMID 32252027, 2020). "Heterozygous mutations in SDHB and SDHD have also been linked to pheochromocytoma-paraganglioma syndromes." (PMID 33426505, 2020). "Familial CPGLs occur as hereditary paraganglioma/pheochromocytoma (PGL/PCC) syndromes, including PGL1, PGL2, PGL3, PGL4, and PGL5, which are associated with germline mutations in the SDHD, SDHAF2, SDHC, SDHB, and SDHA genes, respectively." (PMID 32971818, 2020).
pheochromocytoma (continued). "Germline mutations in succinate dehydrogenase subunit B and D (SDHB and SDHD) are predisposed to hereditary paraganglioma (PGL) and pheochromocytoma (PHEO)." (PMID 30658386, 2019). "SDHB and SDHD mutations are common in pheochromocytoma/paraganglioma, and SDHA mutations and SDHC promoter hypermethylation are relatively common in GISTs4." (PMID 30971719, 2019). "The succinate dehydrogenase subunit B (SDHB) gene is one of the 15 susceptibility genes that have been linked to familial paraganglioma (PGL) and pheochromocytoma (PCC)." (PMID 27573198, 2017). "The estimated mean age of onset of disease for hereditary SDHB-related pheochromocytoma/PGLs is 34 years, but documented cases of malignant PGLs have occurred in childhood before the age of 10 years." (PMID 27896548, 2017). "Germline mutations in the succinate dehydrogenase (SDHA, SDHB, SDHC, SDHD, SDHAF2) or Von Hippel-Lindau (VHL) genes cause hereditary paraganglioma/pheochromocytoma." (PMID 28099933, 2017). "Apart from germ-line mutations such as SDHB, certain somatic mutations including ATRX and MAML3 fusion gene were shown to predict clinical outcome in patient with phaeochromocytoma." (PMID 29166454, 2017). "Germline mutations of the gene encoding succinate dehydrogenase subunit B (SDHB) predispose to head-and-neck-paraganglioma (HNPGL), sympathetic PGL, pheochromocytoma and renal cell carcinoma for which regular surveillance is required." (PMID 27573198, 2017). "Somatic mutations in sporadic pheochromocytoma/paraganglioma has been identified in VHL, RET, SDHB, and SDHD but their frequency was reported to be low." (PMID 26347711, 2015). "Tumor tissue analysis identified LOH at the SDHB locus in three pituitary adenomas and loss of heterozygosity at the MEN1 locus in two pheochromocytomas." (PMID 25494863, 2015). "Quantities of susceptibility genes mutation, including RET, SDHB, and NF-1, have been recognized as being possible to the development of AMH to pheochromocytoma." (PMID 25246937, 2014). "Mutations in the SDHB or SDHD genes predispose patients to glomus tumors and occasionally pheochromocytomas." (PMID 23401807, 2013). "Germline defects in SDH, particularly in SDHA and SDHB, have been detected in several tumor types, including pheochromocytomas, paragangliomas, GISTs, and renal cell carcinomas." (PMID 23888270, 2013). "Promoter methylation of SDHB has been previously reported in primary sporadic phaeochromocytoma (32%) and neuroblastoma (21%)." (PMID 19778456, 2009). "Mutations in SDHB, SDHC and SDHD are also implicated in the formation of phaeochromocytomas, tumors arising in cells derived from the neural crest in the adrenal medulla." (PMID 19432956, 2009). "Recently, SDH genes have been considered as tumour suppressors since germ line inactivating mutations in the SDHB, C and D subunit genes can predispose individuals to hereditary paraganglioma (HPGL) and phaeochromocytoma." (PMID 19849834, 2009). "In patients with familial pheochromocytoma screening for gene mutations in the RET, VHL, SDHB and SDHD gene is recommended since different familial syndromes can be revealed." (PMID 17922902, 2007). "Germline mutations of the SDHD, SDHB and SDHC genes, encoding three of the four subunits of succinate dehydrogenase, are a major cause of hereditary paraganglioma and pheochromocytoma, and demonstrate that these genes are classic tumor suppressors." (PMID 16405730, 2006). "Our findings link pheochromocytomas with mutations in distinct genes—VHL,SDHB, and SDHD—and suggest that mitochondrial complex II inhibition contributes to development of pheochromocytomas with VHL mutation." (PMID 16103922, 2005). "We show here that pheochromocytomas with VHL and SDHB or SDHD mutations form a tight cluster with a clear hypoxia and reduced oxidoreductase signature." (PMID 16103922, 2005). "This will be particularly relevant for SDHB-mutant pheochromocytomas which have been suggested to be more prone to malignancy." (PMID 16103922, 2005).
pheochromocytoma (continued). "For example, ENaC alpha and ASIC1/2 were both found to be expressed in human pheochromocytoma wildtype cells and mutant cells with a knockdown of succinate dehydrogenase subunit B (SDHB), but there were significantly lower levels of the cleaved 60 kDa form of ENaC in SDHB KD cells." (PMID 41462875, 2025). "It shows high sensitivity for pheochromocytomas, both primary and metastatic, particularly in tumors without SDHB/SDHx mutations." (PMID 41268153, 2025). "Nevertheless, MIBG, including 123I and 131I, is not sensitive enough for malignant pheochromocytoma, and Timmers reported a sensitivity of 65% in SDHB mutation‐positive cases." (PMID 38966763, 2024). "Furthermore, the SDHB gene detected through WES is inherited from the mother and is associated with hereditary paraganglioma-pheochromocytoma syndromes (PGL/PCC syndromes) (OMIM 115,310)." (PMID 37726736, 2023). "It was recently shown that the importance of the glutaminolysis pathway promotes proliferation of SDHB-mutated chromaffin cells (PC12, rat pheochromocytoma cell line), suggesting that SDH-associated malignant potential of PCC/PGL is dependent on glutaminase expression." (PMID 35008989, 2022). "Complex II mutations, principally affecting SDHB and SDHD subunits, have been associated with various cancers including hereditary paraganglioma and pheochromocytoma (i.e., neuroendocrine tumors of the paraganglionic tissue), gastrointestinal stromal tumors, and renal cell carcinoma." (PMID 32575796, 2020). "Loss of SDHB protein expression has therefore been used for prognostication in human medicine; in one study, the relationship between the SDH genetic background and SDHB immunohistochemistry sensitivity and specificity in human pheochromocytomas was 94.23%." (PMID 32957698, 2020). "These syndromes involve a group of rare autosomal dominant disorders affecting sympathetic and parasympathetic paraganglia, caused by germline mutations of the genes SDHB, SDHC and SDHD, although some of these mutations can also be detected for patients with apparently sporadic pheochromocytomas." (PMID 23360571, 2013). "Importantly, suppressed SDHB levels were also found in the majority of tumors with VHL mutations and sporadic pheochromocytomas from Cluster 1 tested by immunoblots." (PMID 16103922, 2005). "SDHB immunostaining was highly concordant with the immunoblot findings, suggesting that SDHB downregulation may be a feature of a broader group of pheochromocytomas." (PMID 16103922, 2005). "Also, clinical similarities besides pheochromocytoma have been noted in families with germline mutations of VHL and SDHB." (PMID 16103922, 2005). "Previously, we did not identify somatic SDHB mutations in sporadic phaeochromocytoma, but SDHB maps to 1p36, a region of frequent loss of heterozygosity (LOH) in neuroblastoma as well." (PMID 15505628, 2004). "A phaeochromocytoma sample with a germline SDHB mutation demonstrated 1p allele loss (and no methylation, T12 – see later) consistent with a ‘two hits’ model of tumourigenesis." (PMID 15505628, 2004). "Previously, we did not detect somatic SDHB mutations in 24 sporadic phaeochromocytomas and this has been confirmed by others." (PMID 15505628, 2004). "Cluster 1 PPGLs include pheochromocytomas and abdominal paragangliomas carrying the highest risk of metastatic spread, especially the TCA cycle aberrant tumors carrying genetic variants in enzymes regulating the TCA cycle, including SDHA, SDHB, SDHAF2, FH, MDH2, ISH1 and SLC25A11." (PMID 35205664, 2022). "The major mutations associated with pheochromocytoma are von Hippel-Lindau gene (VHL), REarranged during Transfection (RET) proto-oncogene, neurofibromatosis type 1 gene (NF1), genes encoding four succinate dehydrogenase complex subunits (SDHx; i.e., SDHA, SDHB, SDHC, and SDHD genes)." (PMID 35932074, 2022).
pheochromocytoma (continued). "However, a metabolomic screen of hPheo1 pheochromocytoma cells and SDHB knockdown hPheo1 cells together with cancer tissues with and without SDHx mutations revealed that the polyamines spermidine and spermine were significantly elevated in relation to mutated succinate dehydrogenase." (PMID 34200553, 2021). "Familial HNPGLs together with pheochromocytomas (PCCs) account for about 40% and are associated with four types of hereditary paraganglioma syndromes (PGL1–5) caused by mutations in the following genes: SDHD (PGL1), SDHAF2 (PGL2), SDHC (PGL3), SDHB (PGL4), and SDHA (PGL5)." (PMID 33391357, 2020). "Moreover, recent studies indicate that up to 25% of pheochromocytoma patients have a genetic background (NF1, VHL, SDHD, SDHB or RET gene mutations) and thus both the patients and their closest blood relatives require wide multidisciplinary diagnostics as well as long-term follow-up." (PMID 31137898, 2019). "If an SDHB germline mutation is identified in a patient with HNPGL, the clinician should be aware of the variable manifestations of the SDHB‐linked tumour syndrome, the risk of catecholamine excess, concurrent phaeochromocytoma, and association with non‐paraganglionic tumours." (PMID 29951630, 2018). "In addition, shRNA was used to knockdown other genes associated with pheochromocytoma pathogenesis such as SDHB, yet markers for re-differentiation were not up-regulated either." (PMID 23785438, 2013). "Even though germline SDHB mutations are an important cause of phaeochromocytoma susceptibility, we did not identify somatic SDHB mutations in phaeochromocytoma so far." (PMID 15505628, 2004). "Immunohistochemical staining of human PPGL tissues with different hereditary backgrounds confirmed elevated SUCNR1 protein expression in SDHB PPGLs and SDHD HNPs, compared to VHL pheochromocytomas." (PMID 33776908, 2021). "Tumor tissue analysis identified LOH at the SDHB locus in three pituitary adenomas and LOH at the MEN1 locus in two pheochromocytomas." (PMID 25494863, 2015). "It is now known that SDHB and SDHD, together with VHL and RET, play a major role in hereditary pheochromocytoma." (PMID 16405730, 2006). "This study also describes a number of sporadic head and neck paragangliomas with low SDHB staining; these tumors might correspond with Cluster 1 pheochromocytomas for which no detectable mutation was identified and that also appear to arise from disruption of related pathways." (PMID 16103922, 2005). "In two cell line models, HEK293 and mouse pheochromocytoma cell line (MPC) 9/3L, exposure to the hypoxia-mimetic agent cobalt chloride reduced SDHB protein expression." (PMID 16103922, 2005). "Though this relationship is not specifically related to a germline variant, RET, SDHB, SDHC, SDHD, and SDHAF2 each include a predisposition of developing pheochromocytoma and thus must be considered." (PMID 35685436, 2022). "In this study, it was found that 24% of the patients who presented with nonsyndromic pheochromocytoma and without family history of the disease had mutations in VHL, RET, SDHD, and SDHB genes." (PMID 24899893, 2014). "Similar to what we found in primary pheochromocytomas, no decrease in SDHB mRNA was detected when these cell lines were treated with hypoxia-mimetic drugs (data not shown), suggesting that a posttranscriptional phenomenon is related to these findings." (PMID 16103922, 2005). "In this study, we observed that metformin exerts an antiproliferative effect on 2D and 3D cultures of pheochromocytoma mouse tumour tissue (MTT), either silenced or not for the SDHB subunit." (PMID 35884532, 2022). "LOH at the SDHB locus in the PA samples and LOH at the MEN1 locus in the pheochromocytoma samples was demonstrated, suggesting, although not proving, the pathogenic role of these genes in these nonclassically disease-specific tissues." (PMID 25494863, 2015).
metastatic disease (77 papers, 2009 to 2026). "Meta-analyses have also been conducted in the other SDH variants, revealing the metastatic disease prevalence of 23% to 31% for SDHB, 23% for SDHC, 16% for SDHA, and 6% to 8% for SDHD." (PMID 41183483, 2026). "Patients with the germline SDHB variant presented as the largest group with metastatic disease, accounting for 926 out of a total of 1789 metastatic events." (PMID 41183483, 2026). "Although they all have SDHB variant and extensive metastatic disease of the spine, this patient was significantly different from our reported patient in imaging and symptoms." (PMID 40917352, 2025). "Among them, germline mutations in SDHB are the most consistently recognized predictor of aggressive or metastatic disease." (PMID 41427045, 2025). "18F-FDG PET/CT plays an important role in detecting and monitoring BM in PPGL, especially in metastatic disease and tumors with SDHB mutations." (PMID 41268153, 2025). "Regarding the clinical features, numerous retrospective studies suggest that patients with SDHB mutations are more susceptible to experiencing metastatic disease." (PMID 40150683, 2025). "The incidence of metastatic disease varies by tumor site and genotype, affecting approximately 10% of PHEOs and 15–35% of abdominal PGLs, with higher rates observed in SDHB mutation carriers." (PMID 41427045, 2025). "SDHB-related PPGLs carry the highest risk of metastatic disease, which has been estimated to be 30% in some studies." (PMID 40063004, 2025). "This study aimed to evaluate the applicability of succinate measurement as a potential biomarker in PGLs within our cohort, including patients with pathogenic variants beyond SDHB and those with metastatic disease." (PMID 41026309, 2025). "The authors reported an association of SSTR2 expression with SDHB/SDHx mutations and metastatic disease, and confirmed a high disease control rate of somatostatin receptor-based therapies in metastatic PPGLs." (PMID 40149362, 2025). "[18F]-FDG PET is also very sensitive for the detection of metastatic disease in patients with the presence of SDHB mutations." (PMID 40149362, 2025). "Multiple studies have demonstrated that SDHB mutations are associated with an increased risk of metastatic disease (up to 60%)." (PMID 41306434, 2025). "SDHB mutation is frequently associated with metastatic disease and dominant secretion of noradrenaline and/or dopamine." (PMID 39129823, 2024). "Both recurrent and metastatic disease were significantly associated with SDHB pathogenic variants (p = 0.006)." (PMID 38849646, 2024). "We performed a comprehensive genomic analysis of SDHB-associated PCPG thereby creating a data resource to understand development of metastatic disease in these patients." (PMID 38978571, 2024). "In a multivariate analysis, SSTR2 IHC positivity was significantly associated with metastatic disease (P < .001), independently of germline SDHB mutations or tumor size." (PMID 36946182, 2023). "SDHx and specifically SDHB mutations were associated with extra-adrenal disease, and germline SDHB mutations were associated with metastatic disease (P < .001)." (PMID 36946182, 2023). "In particular, patients with SDHB mutation—which is often inherited as an autosomal dominant germline—have a high risk of metastatic disease occurrence." (PMID 37111596, 2023). "PPGLs with mutations in succinate dehydrogenase subunit B (SDHB) belong to cluster 1A and are associated with a higher risk of metastatic disease than other hereditary PPGLs." (PMID 36946182, 2023). "Metastatic disease is rare, but almost half of the cases are associated with SDHB mutation-related PPGL, as patients with germline SDHB mutation have an overall 25% to 50% risk of developing metastatic disease." (PMID 35163370, 2022). "A small number of SDHB-related PPGLs have been reported in 6-year-old children, which is associated with a high risk of metastatic diseases compared to other SDHx mutation carriers." (PMID 35158861, 2022).